BTN2A1 (butyrophilin subfamily 2 member A1)
Diseases named in the same sentence as BTN2A1 in open-access papers (continued):
Sharing a sentence is not in itself a finding about the gene and the disease.
tumor (continued). "It was found that the destruction of tumor cells by V9V Gamma 2 T cells required BTN2A1 expression." (PMID 38922530, 2024). "Whether the use of P4 treatment of NPC cells can achieve physiological concentration of IL-22 for BTN2A1 induction remains to be investigated, as the amount produced is most likely less than tumor-resident lymphoid cells." (PMID 39769218, 2024). "Moreover, Vδ2-TCR+ cells seemed to be located in regions where tumor cells expressed BTN2A1 and were found to coincide with cells that co-expressed PD-L1." (PMID 38077396, 2023). "However, there are also regions in the tumor that only expressed BTN2A1, BTN3A1/PD-L1 or BTN2A1/BTN3A1/PD-L1." (PMID 38077396, 2023). "Tumoral pAgs bind the intracellular domain of BTN3A1, which is associated and comprises complexes with BTN2A1, and BTN2A1 can be recognized directly by TCR Vγ9 chain, while IPP is overproduced by the dysregulated mevalonate pathway in cancer cells, which activates Vγ9Vδ2 T cells." (PMID 37508545, 2023). "According to the current model, microbe- or tumour-derived pyrophosphates bind to the intracellular B30.2 domain of BTN3A1 which then interacts with BTN2A1 to induce a conformational alteration of the extracellular BTN3A1/2A1 complex which is recognized by the γδ TCR." (PMID 38090581, 2023). "We can hypothesize that high level of circulating BTN2A1 could lead to Vγ9Vδ2 T-cells exhaustion that facilitate tumor immune escape mechanisms, and/or activate Vγ9Vδ2 T cells with pro-tumorigenic characteristics, and explain the poorer outcomes of patients with high level of circulating BTN2A1." (PMID 33959132, 2021). "For instance, it has been reported a bispecific γδ T cell engager (GADLEN), containing heterodimeric BTN2A1 and BTN3A1 extracellular domains (ECD) fused via inert Fc linkers to scFv domain targeting a tumor-antigen (CD19 or CD20)." (PMID 39144149, 2024). "In comparison, non-P4 treated tumor had considerably less BTN2A1 expression and Vδ2-TCR+ cells appear to be more randomly distributed in the tumor." (PMID 36632221, 2023). "As previously discussed, Vδ2+ TCRs bind to activated BTN2A1 protein sentries, bringing CD8+ and CD4+ T cells within close proximity to stressed tumor cells." (PMID 36212425, 2022). "Following phosphoantigen binding to the intracellular B30.2 domains of BTN3A1 in tumor cells, BTN3A1 undergoes a conformational change and promotes the interaction between BTN2A1 and BTN3A1 intracellular domains." (PMID 36685942, 2022). "Following phosphoantigen binding to the intracellular B30.2 domains of BTN3A1 in tumor or pathogen-infected cells, BTN3A1 undergoes a conformational change and promotes the interaction between BTN2A1 and BTN3A1 intracellular domains." (PMID 35880177, 2022). "In addition, both γδ T and NK cells degranulated and consistently induced lysis in a panel of NB cell lines and patient-derived 3D tumor spheres expressing B7H6, calreticulin, HA-TAG, BTN2A1, and BTN3A1/2/3 consistently." (PMID 41694338, 2026). "Therefore, BTN2A1 serves as an immediate ligand for Vγ9Vδ2 TCR and is necessary for the Vγ9Vδ2 T cell-induced destruction of tumor cells." (PMID 40558272, 2025). "Because the expression of BTN2A1 and BTN3A can be altered in tumor and infected cells, combining TEGs and OVs could potentially enhance the anti-tumor response." (PMID 40076788, 2025). "5.9% of cells co-expressed BTN2A1/BTN3A1, suggesting that Vδ2 T cells with full functional capacity could potentially target 32.7% of cells in the tumor if unhindered by the presence of PD-L1 or blocked by αPD-1." (PMID 38077396, 2023). "We have recently developed a novel T cell engager concept by utilizing γ9δ2TCR as tumor targeting domain, named gamma delta TCR anti-CD3 bispecific molecule (GAB), targeting the phosphoantigen-dependent orchestration of BTN2A1 and BTN3A1 at the surface of cancer cells." (PMID 36685546, 2022).
tumor (continued). "Vγ9δ2 T cells, a specific γδT cell subset mainly found in the blood, recognize members of the butyrophilin (BTN) family, namely BTN2A1, through the gamma chain of their Vγ9δ2TCR, and additionally require BTN3A1 expression on the tumor cells for full activation." (PMID 36685546, 2022). "Finally, since BTN2A1 and BTN3A1 are not only expressed on tumor cells but also on Vg9Vd2 T cells and other T cells, the potential for (self-)elimination of immune cells should be taken into consideration when evaluating the safety profile and the presence of immune populations in peripheral blood." (PMID 39144149, 2024). "In addition, a more convenient method to detect BTN2A1 and BTN3A1 expression would be necessary.Dysregulation of the mevalonate pathway is common in tumor cells, leading to the accumulation of both DMAPP and IPP, which could be recognized by Vγ9Vδ2 T cells." (PMID 37770968, 2023). "No BTN2A1 or BTN3A1 expression was detected in tumor-adjacent tissue or normal brain tissue." (PMID 37770968, 2023). "Thus, the expression pattern, regulatory mechanism, and αβ T cell inhibiting effect of BTN3A1 make it highly similar to PD‐L1, further elaborating the notion that BTN3A1 expressed by tumor cells may be another immune checkpoint molecule rather than merely activate Vγ9Vδ2 T cells with BTN2A1 in CC." (PMID 40091603, 2025). "On the other hand, Payne and colleagues reported that, in its spontaneous conformation without BTN2A1, BTN3A1 inhibited tumor-reactive αβ T cell activation." (PMID 37629075, 2023).
cancer (18 papers, 2020 to 2025). A tumor composed of atypical neoplastic, often pleomorphic cells that invade other tissues. "With regard to NLRC5, we did not witness its role in the transcriptional induction of endogenous BTN2A1 and found just a weak correlation between NLRC5 and BTN2A1 transcript abundance in M. tuberculosis patients and ‘The Cancer Genome Atlas’ cancer samples." (PMID 39035010, 2024). "The expression of the BTN2A1/BTN3A1 complex can trigger the activation of Vγ9Vδ2TCR, and the expression of BTN2A1 in cancer cells is related to the cytotoxicity of Vγ9Vδ2T cells." (PMID 36793048, 2023). "Current studies have shown that BTN2A1 expression on target (cancer) cells is correlated with γδ T cell cytotoxicity." (PMID 37629075, 2023). "Targeting BTN3A and BTN2A1 holds promise as a therapeutic strategy for treating cancers and infectious diseases." (PMID 37674084, 2023). "The anti-BTN2A1 monoclonal antibodies help to mitigate the cytotoxic effects of Vγ9Vδ2+ T cells on cancer cells." (PMID 36276933, 2022). "Third, combination of BRRF1 and LMP1 transduction could be attempted in various cancers to determine if they will achieve high expression of BTN2A1/BTN3A1 proteins, especially among those NPC cell lines unresponsive to BRRF1 alone." (PMID 39769218, 2024). "BTN3A1-stimulating antibodies or IPP transformed the immunosuppressive molecule conformation of BTN3A1 into an immunostimulatory one and elicited coordinated restoration of αβ T cell effector activity and BTN2A1-dependent γδ T lymphocyte cytotoxicity against BTN3A1+ cancer cells." (PMID 37629075, 2023). "Interestingly, the expression of BTN-family members including BTN2A1/3A1, crucial in pAg-mediated γδ T cell activation was largely down-regulated in the cancer isolates." (PMID 38090581, 2023). "As previous work also identified somatic mutations of NLRC5 in 4.8% of EBV-positive NPCs 40, but whether these mutations affect BTN2A1 and BTN3A1 expression remains to be investigated in clinical NPC cancers." (PMID 36632221, 2023). "Recent studies show that BTN2A1, which binds directly to the TCRs via germline-encoded regions of Vγ9, is also essential to BTN3A-mediated γδ T cell cytotoxicity and BTN2A1 expression at the plasma membrane of cancer cells correlated with γδ T cell cytotoxicity." (PMID 34445615, 2021). "We also demonstrated the involvement of BTN3A1 and BTN2A1, crucial molecules for γδ T cell activation, as well as differential expression of PDL1/CD274 in cancer, E6/E7+ and healthy organoids." (PMID 38090581, 2023). "Anti-BTN2A monoclonal antibodies (mAbs) inhibit BTN2A1 biding to the γδ TCR and modulate γδ T cell killing of cancer cells." (PMID 34445615, 2021). "Within this context, we show that targeting BTN2A1 and BTN3A through TEGs might add to the arsenal of cellular cancer immune therapies for DMG." (PMID 40076788, 2025). "BTN2A1, together with BTN3A1, is present on the surface of antigen-presenting cells and cancer cells, and after the internal domain of BTN3A1 binds phosphoantigens, conformational changes in both molecules occur, allowing BTN2A1 to bind to the Vγ9 region of the TCR γδ." (PMID 40276509, 2025). "Thus, BTN2A1 and BTN3A1 molecules are particularly important for consideration in studying the effects of Vγ9Vδ2 T cells in immunotherapy against cancer." (PMID 39769218, 2024). "However, our blocking studies using inhibitory antibodies against BTN2A1 and BTN3A1 clearly indicated the significance of these BTN molecules in triggering the cytotoxic activity of γδ T cells against HPV+ and cancer organoids., in line with previous reports." (PMID 38090581, 2023).
infection (4 papers, 2015 to 2025). The state of being infected such as from the introduction of a foreign agent such as serum, vaccine, antigenic substance or organism. "Studies have shown that through the binding to P-Ags presented by BTN3A1 and BTN2A1 on infected or malignant cells, γδ T cells could be activated, proliferate rapidly, and release cytokines to induce anti-infection or antitumor responses." (PMID 33101298, 2020). "Studies have shown that through binding to P-Ags presented by BTN3A1 and BTN2A1 on infected or malignant cells, γδ T cells could be activated, proliferate rapidly, and induce anti-infection or antitumor responses through IFN-γ production." (PMID 33101298, 2020). "Expression of BTN2A1 and BTN3A in SU-DIPG-IV and VUMC-DIPG-G was investigated at 2 days post-infection with D24-RGD and R124." (PMID 40076788, 2025). "We next tested the expression of BTN2A1 and IGSF8 during infection with the AD169VarL virus and a BAC derived AD169VarL virus, in which the US2-US6 region was deleted (the region in which the BAC cassette was inserted)." (PMID 26599541, 2015). "These cells were then infected with HCMV and the kinetics of BTN2A1 and IGSF8 expression along infection was evaluated by western blot analysis." (PMID 26599541, 2015). "In contrast, the counterpart of BTN3A, namely BTN2A1, which is required for successful interaction with the γ9 chain of the γ9δ2TCR, was not increased on the cell surface after OV infection." (PMID 40076788, 2025).
brain disorder (1 paper, 2025). A disease affecting the brain or part of the brain. "Of the significant reverse MR relationships, the brain disorders demonstrated associations with the increased expression of six proteins (PAMR1, MAVS, F11R, REN, GER and LEPR) and decreased expression of three proteins (TNFRSF4, BTN2A1, ENPP6)." (PMID 40456753, 2025).
hematologic cancer (1 paper, 2024). "Together with BTN2A1, BTN3As regulate non-conventional Vγ9Vδ2 T cell responses triggered by selected metabolites of microbial origin or accumulating in hematologic cancer cells." (PMID 39035010, 2024).
BTN2A1 also shares sentences with these, for which no sentence is quoted: celiac disease (2 papers); chronic kidney disease (2); renal cell carcinoma (2); allergic rhinitis (1); Angina (1); bipolar disorder (1); bladder cancer (1); cardiovascular diseases (1); essential hypertension (1); gastric tumor (1); Hiatus hernia (1); infectious disease (1); inflammatory bowel disease (1); ischemic stroke (1); neuroblastoma (1); psoriasis (1); rheumatoid arthritis (1); serous ovarian cancer (1); Stroke (1); type 1 diabetes (1); type 2 diabetes mellitus (1); ulcerative colitis (1).